MTOR (mechanistic target of rapamycin kinase)
Diseases named in the same sentence as MTOR in open-access papers (continued):
Sharing a sentence is not in itself a finding about the gene and the disease.
cancer (continued). "Mechanistically, it is suspected that metformin activates the AMPK signaling and inhibits the mTOR pathway to elicit an anti-cancer response." (PMID 35884561, 2022). "Detection of somatic variants in cancer and PROS can guide personalized treatment including consideration of inhibitors of the PI3K/AKT/mTOR signaling pathway." (PMID 36636551, 2022). "Our findings suggest a therapeutic application for PI3K/mTOR inhibitors in treating RNF43_p.G659fs mutant cancers." (PMID 35676246, 2022). "mTOR pathway either participates in force-induced molecular mechanisms that confer resistance to applied treatment or mTOR targeting holds promise for cancer cells’ resensitization to chemotherapy, targeted therapy, or radiotherapy." (PMID 35163745, 2022). "The PI3K/Akt/mTOR pathway is a crucial signaling cascade in living organisms that has to be activated in a variety of cancers and to regulate cell proliferation, invasion, and migration." (PMID 35178352, 2022). "As has been pointed out before, the PI3K/AKT/mTOR mediated transcription repression of the viral E6/E7 oncogene can only be observed in hypoxia condition, indicating the connection between the PI3K/AKT/mTOR activity and metabolic transition in cancer cells." (PMID 36061190, 2022). "Our findings that NOP56 KD cells are exposed to higher levels of metabolic ROS and display a greater dependency on UPR-activated mTOR signaling suggest a synthetic lethal vulnerability in KRAS-mutant cancer." (PMID 35039048, 2022). "The results suggest that viperin induction via the PI3K/AKT/mTOR/HIF-1α pathway as well as the JAK/STAT pathway allowed cancer cells to rapidly adapt to the changing conditions in the TME through metabolic reprogramming." (PMID 36227691, 2022). "While mTOR inhibitor has a limited efficacy in cancer cells, the combination of mTOR inhibitors and other drugs demonstrated synergistic effects." (PMID 36072341, 2022). "mTOR is a key node inPI3K/Akt/mTOR pathway and unusual mTOR signaling can promote the development and progression of various cancers.Thus, developing clinical drugs based on mTOR kinase inhibition is of great interest." (PMID 36909695, 2022). "The MEK/ERK/mTOR signaling pathway is a classical pathway that not only promotes angiogenesis and cell progression but also plays an important role in various human malignant tumors." (PMID 35418575, 2022). "We, therefore, tested a drug library on the three tumor organoid models that contained small molecules against a wide range of cancer‐associated pathways, that is, EGFR, MAPK, BTK, and PI3K/mTOR." (PMID 35993110, 2022). "Further, no significant change in sensitivity to OXPHOS inhibition was detected after baseline mTOR activity was comprised in both sensitive and resistant cancer cells." (PMID 36382559, 2022). "A decrease in the mTOR level before treatment in a tumor was found in patients with a partial response, complete response, and cancer progression." (PMID 35877414, 2022). "In vitro, voxtalisib inhibited the phosphorylation of PI3K and controlled mTOR effector incorporation in malignant tumor cells." (PMID 36539659, 2022). "Overactivation of the PI3K-Akt-mTOR signaling pathway has been demonstrated in many different cancer types as a mechanism for tumor growth and therapeutic resistance." (PMID 35525914, 2022). "Among them, we observed overexpression of ACLY significantly increased the levels of intracellular free fatty acid and triglyceride, and activated AKT/mTOR pathway to promote cancer development." (PMID 36064336, 2022). "Conversely, activation of the mTOR pathway confers increased chemosensitivity in cancer cells with genetic ablation of TSC1/2." (PMID 36396656, 2022). "Studies have suggested mTORC1 activation contributes to elevated cancer migration, invasion, and metastasis, while mTOR inhibition results in mitochondrial elongation and branching, and the morphology can be completely reversed by overexpressing MTFP1." (PMID 35589683, 2022).
cancer (continued). "The abnormal activation of PI3K/Akt/mTOR signaling pathway has been confirmed in a variety of cancer cells." (PMID 36213832, 2022). "The mTOR signal is highly activated in most cancers, especially in the process of cell transformation, growth, and survival." (PMID 36159561, 2022). "Metformin has also been shown to activate AMPK, a critical energy sensor in cellular metabolism, and to limit cancer cell proliferation via the negative regulation of mTOR needed for tumor survival." (PMID 35225948, 2022). "Mechanistically, for the first time, we revealed that FGFR inhibition suppressed HK2 gene transcription via inhibiting mTOR in FGFRi-sensitive in vitro and in vivo cancer models with different FGFR1-4 anomalies." (PMID 36168616, 2022). "Baicalein in combination with cisplatin effectively reduced p-AKT and p-mTOR in drug-resistant SGC-7901 cancer cells." (PMID 35955525, 2022). "P-S6, the key downstream effector of mTOR/S6K pathway, is involved in the occurrence and development of many cancers." (PMID 35596155, 2022). "PI3K inhibitors can improve the prognosis of cancer patients through blocking PI3K/AKT/mTOR signaling pathway." (PMID 35778737, 2022). "Previous studies have also indicated that regulating the mTOR signaling pathway can sensitize cancer cells to anticancer drugs." (PMID 36289218, 2022). "Depletion of NOP56 impairs the response to oxidative stress, which renders KRAS-mutant cancer cells highly dependent on mTOR signaling for survival and particularly vulnerable to mTOR inhibition." (PMID 35039048, 2022). "We have also revealed a novel synthetic lethality between NOP56 depletion and mTOR inhibitors that occurs by impeding the homeostatic mechanism of ROS in KRAS-mutant cancer cells." (PMID 35039048, 2022). "Taken together, the tissue-agnostic therapeutic management of a pan-cancer cohort of patients with mTOR pathway aberrations posed several major challenges, including the weak activity of mTOR inhibitors and the long turnaround time." (PMID 35454843, 2022). "PD also protects against inflammatory damage and inhibits cell proliferation, survival, and protein synthesis by targeting the PI3K/Akt/mTOR signaling pathway, which is activated in cancer cells." (PMID 36364001, 2022). "This signaling is connected to a downstream PI3K/Akt/mTOR pathway, which plays a key role in controlling cancer cell proliferation and migration." (PMID 35243817, 2022). "PI3K/Akt/mTOR pathway has an integral role in cancer cells; for example, it has been estimated to be activated in 70% of all BCs." (PMID 35986321, 2022). "In cancer cells, the overactivation of oncogenic mTOR signaling pathway is frequently observed and mTOR inhibitors have been actively developed in recent years." (PMID 36072341, 2022). "CAMKK2-regulated differences in cancer cell size and mTOR signaling (assessed by p-S6 IHC) combined with the sustained alterations in circulating insulin levels suggest that insulin mediates CAMKK2’s effects on cancer via control of systemic metabolism." (PMID 35741020, 2022). "Collectively, the deficiency of the LKB1-AMPK axis in cancers reactivates PROX1 to sustain intracellular BCAA pools and mTOR signalling, facilitating tumourigenesis and aggressiveness." (PMID 36433955, 2022). "Everolimus, a first generation mTOR inhibitor, is the more frequently used option in cancer treatment." (PMID 35216092, 2022). "Studies have demonstrated that activation of the AKT/mTOR pathway enhances BC resistance to Adriamycin and promotes cancer development." (PMID 36105365, 2022). "In this, berberine plays an important role in cancer management through inhibition of the PI3K/AKT/mTOR pathway." (PMID 36144625, 2022). "The mTOR signaling pathway often becomes poorly activated during tumor progression and contributes to tumorigenesis by deregulating cancer cell proliferation." (PMID 36185289, 2022).
cancer (continued). "Collectively, these results prove that miR-199a-3p/5p can act as cancer suppressor genes to inhibit the mTOR signaling pathway by targeting Rheb, which in turn inhibits the regulatory process of NSCLC." (PMID 35844793, 2022). "For instance, two major pathways that link the cellular environment to gene expression, the HIF and mTOR pathways, are both dysregulated in many cancers." (PMID 36097292, 2022). "It prevents ubiquitination, which activates the oncogenic AKT/mTOR signaling pathway and accelerates cancer progression." (PMID 36230492, 2022). "When analyzing the list of 872 immune P-proteins, we focused on major cancer effectors and especially on the serine/threonine-protein kinase mTOR, which is an important immuno-oncogenic player." (PMID 35495117, 2022). "Deregulation of mTOR has been found in various human cancers, including resistant ones such as TNBCs." (PMID 36499000, 2022). "The efficacy of the mTOR inhibitor sirolimus, and targeted therapies that block the Ras/BRAF/MEK/ERK1/2 and PI3KCA/AKT/mTOR pathways in many types of cancer and VAs, further supports the critical role of ESC-like cells in the pathogenesis of these conditions." (PMID 35574555, 2022). "Currently, systemic mTOR inhibition is mostly utilized to treat cancer and for immunosuppression following organ transplantation." (PMID 35845058, 2022). "In the field of BC, the mTOR inhibitor, everolimus, has been used as an antitumour treatment option in this cancer by impeding autophagy and inducing dormancy, which highlights very significant aspects of BC therapy; keeping the cells dormant." (PMID 35563661, 2022). "PI3K/Akt/mTOR inhibition to target cancer cell metabolism through drugs (such as Gleevec) has a side effect of affecting metabolism in a systemic fashion." (PMID 35392088, 2022). "The mTOR signaling pathway is activated by AKT and associated with several fundamental cellular processes 17, such as autophagy 18, and cancer." (PMID 35414770, 2022). "PI3K/AKT and the mammalian target of rapamycin (mTOR) signaling pathway inevitably plays a pivotal role in cancer progression 20-22." (PMID 35414774, 2022). "mTOR (mammalian target of rapamycin) signaling is commonly activated in tumors and plays a regulatory role in tumorigenesis and cancer development." (PMID 35453663, 2022). "Knockdown of EpCAM in prostate cancer cell lines inactivated the PI3K/AKT/mTOR signaling pathway, thus sensitizing the cancer cells to chemo/radio-therapy." (PMID 36369033, 2022). "It was demonstrated in many studies that the phosphatidylinositol 3-kinase (PI3K)/Protein kinase B (Akt)/mechanistic target of rapamycin (mTOR) pathway is a promising target for cancer therapy." (PMID 36500361, 2022). "Recently, MTOR-specific inhibitors were examined as potential anti-cancer agents and showed anti-cancer activity in several patients with advanced HCC." (PMID 35159256, 2022). "The PI3K/AKT/mTOR signalling pathway is constitutively active in several cancer processes and plays an important role in carcinogenesis and development." (PMID 36295538, 2022). "The mammalian target of rapamycin (mTOR) is a highly conserved serine/threonine-protein kinase, which regulates many biological processes related to metabolism, cancer, immune function, and aging." (PMID 36428613, 2022). "It has been reported that mTOR exerts important functions in cancer stem cells through the specific functions related to stemness." (PMID 35558559, 2022). "The mechanistic target of rapamycin (mTOR) pathway regulates fundamental cell processes and dysregulation of the pathway is relevant for the progression of cancer." (PMID 35106465, 2022). "PTEN, whose activity antagonizes the PI3K/Akt/mTOR pathway and therefore represses tumor cell growth and survival, is one of the most frequently disrupted tumor suppressors in cancer." (PMID 35260738, 2022).
cancer (continued). "Inhibitors of PI3K/AKT/mTOR pathway not only increases the radiosensitivity of HNSCC cells but also reverses the radiation-sensitive effect of radiation-resistant cancer cells." (PMID 36555391, 2022). "VP-BEZ235, another autophagy inhibitor, is a novel and potent dual PI3K/mTOR inhibitor which results in anti-proliferative and anti-tumor activity in cancer cells; it is currently in clinical trials for advanced solid tumors." (PMID 35887232, 2022). "Promoting the PI3K/AKT/mTOR pathway improves glucose transporter levels, increasing the rate of glycolysis, which promotes cancer progression." (PMID 36276933, 2022). "Magnolol inactivated the tyrosine kinase receptor EGFR and VEGFR2 as well as upregulating PTEN activity, thereby abolishing the abnormal PI3K/Akt/mTOR signaling in cancer cells." (PMID 36234977, 2022). "The mechanistic target of rapamycin (mTOR) also depends on IGF1R signaling in cancer cells and directly leads to protein biosynthesis and anabolic metabolism." (PMID 35574343, 2022). "We have given special attention to betulinic acid mediated regulation of JAK/STAT, VEGF, EGF/EGFR, TRAIL/TRAIL-R, AKT/mTOR and ubiquitination pathways in the inhibition of cancer." (PMID 36615262, 2022). "This work by Gu and co-workers adds a fourth activity (ferroptosis) to three anti-cancer activities proposed in 2012: cycle arrest, apoptosis, and rapamycin-like gerosuppression or, in simple words, mTOR inhibition." (PMID 36052376, 2022). "PI3K/Akt/mTOR signaling is involved in cellular growth, proliferation, and cell cycle progression in various cancer cells." (PMID 35331184, 2022). "mTOR inhibitors (e.g., rapamycin, second-generation mTOR inhibitors) have been approved for the treatment of several types of cancer and more of them are being actively tested in clinical trials." (PMID 35831271, 2022). "When the PI3K/AKT/mTOR pathway is abnormally activated, it promotes the occurrence and development of various cancers, including EC." (PMID 36090016, 2022). "Previous studies have revealed that Akt/mTOR signalling pathway plays an important role in progression of cancers." (PMID 35315581, 2022). "Multiple human cancer cell lines demonstrate a paradoxical increase in eIF4E phosphorylation under mTOR inhibition with rapamycin, attributable to MNK activity." (PMID 35383235, 2022). "Characterization of the key deregulated oncogenic signaling pathways revealed their convergence to activate the mammalian target of rapamycin (mTOR), in which signaling plays an essential role in the regulation of cancer growth and survival." (PMID 36612012, 2022). "The enhanced glutamine in cancer cells activates mTOR signal transduction, inhibits endoplasmic reticulum stress, and promotes protein synthesis, thereby promoting tumor growth and proliferation." (PMID 35844514, 2022). "Growth factor-mediated signaling such as the PI3K/AKT/mTOR signaling pathway is responsible for cancer proliferation and cell survival." (PMID 35538133, 2022). "Activating PIK3CA gene mutations upregulate intracellular signalling via the PI3K–protein kinase T (Akt)–mammalian target of rapamycin (mTOR) pathway, contributing to multiple hallmarks of cancer, such as resisting cell death and uncontrolled proliferation." (PMID 35267596, 2022). "Altogether, our data indicate that PEBP4 participates in regulation of Akt/mTOR, leading to increased proliferation, migration, invasion, and metastasis of cancer cells." (PMID 35955931, 2022). "Anthocyanins work against cancer by reducing oxidative stress, regulation of Akt/mTOR, p38, and survivin, preventing cancer cell proliferation and promoting apoptosis." (PMID 35889793, 2022).
cancer (continued). "In these malignancies, USP10 was shown to inhibit c-Myc transcription, and AKT/mTOR activation to inhibit cancer cell growth." (PMID 36543867, 2022). "In fact, Hsp90 inhibitors have been shown to synergize with PI3K/Akt/mTOR inhibitors in preclinical studies for the treatment of various cancers." (PMID 35883484, 2022). "RpS6 (ribosomal protein S6) is another protein of interest; it is a downstream effector of both the ERK and the mTOR pathways, and it is essential for the protein synthesis required during cancer progression." (PMID 35884900, 2022). "Some drugs act as translational-specific inhibitors in cancer treatment, such as rapamycin, an mTOR inhibitor, one of the most critical translational regulators that impair cancer metabolism and has been extensively researched as a cancer drug." (PMID 36432484, 2022). "PTEN is a crucial tumor suppressor gene inhibiting phosphatidylinositol 3-kinase (PI3K)/protein kinase B (AKT)/mammalian target of rapamycin (mTOR) pathway, which is often aberrant in cancer." (PMID 35267503, 2022). "The PI3K/Akt signaling cascade and its downstream signaling pathways, such as the target of rapamycin (mTOR), play important roles in cancer metabolism, MDR, and progression." (PMID 36297616, 2022). "As a GTPase, RAB3IP is involved in the mTOR signaling pathway and regulates autophagy in cancer cells." (PMID 36353541, 2022). "In summary, we demonstrated that mTOR is highly expressed while miR-99b-5p is downregulated in PCa and other cancers." (PMID 36077039, 2022). "Phosphatidylinositol 3-kinase (PI3K)/Akt/mammalian target of rapamycin (mTOR) signaling is one of the most important intracellular signaling pathways that is related to cell proliferation, motility, survival and apoptosis of cancer cells." (PMID 36506551, 2022). "Activation of the Akt/mTOR pathway can inhibit autophagy, which is critical for cancer cell growth and survival." (PMID 36612260, 2022). "After enrichment analyses, it was detected that these genes were enriched in various cancer pathways, including the phosphatidylinositol signaling system and mammalian target of rapamycin (mTOR) signaling pathway." (PMID 35486636, 2022). "The PI3K/AKT/mTOR pathway is frequently dysregulated in cancer, and ROS can act as upstream regulators of the pathway." (PMID 35795862, 2022). "Several previous studies have shown that the phosphatidylinositol 3-kinase (PI3K)/Akt/mammalian target of rapamycin (mTOR)/70-kDa ribosomal protein S6 kinase (p70 S6K) pathway plays a critical role in regulating the growth of both normal and cancer cells." (PMID 35110531, 2022). "While many targets of PA signaling have been identified, the most critical target of PA in cancer cells is likely to be mTOR, the mammalian target of rapamycin." (PMID 35115500, 2022). "Overall, the combination of Rhein and RAD001 exert synergistic cancer prevention in GC via PI3K/Akt/mTOR pathway." (PMID 35209807, 2022). "PI3K/AKT/mTOR has been shown to be frequently activated in various cancer pathways and is an important target for cancer therapy." (PMID 36429034, 2022). "Combined, these findings indicated that ZDQ-0620 has potential as a novel anti-cancer drug targeting the PI3K/AKT/mTOR pathway in CRC to inhibit tumor initiation and progression." (PMID 35311154, 2022). "It has been discussed the function of the PI3K/AKT/mTOR signaling pathway related to tumor mechanisms in many types of cancers." (PMID 35414774, 2022). "These agents affect the modulation of autophagy via PI3K/Akt/mTOR pathway inhibition in different cancer cells." (PMID 36428613, 2022). "For example, the expression of programmed cell death 1 ligand 1 (PD-L1) in cancer cells can drive the activation of Akt-mTOR and glycolysis in cancer cells, increase glucose uptake, and enhance the ability to compete with T cells for glucose." (PMID 35444235, 2022).